CDH10 (cadherin 10)
Description:
Cadherins are calcium-dependent cell adhesion proteins. They preferentially interact with themselves in a homophilic manner in connecting cells; cadherins may thus contribute to the sorting of heterogeneous cell types.
Tractability: Antibody: UniProt places it where antibodies can reach, with high confidence; its Gene Ontology location is reachable by antibodies, with high confidence; UniProt predicts a signal peptide or a membrane-spanning region. PROTAC: its protein half-life has been measured.
Gene: Protein-coding gene on chromosome 5 (24,487,099 to 24,644,978, reverse strand). Ensembl gene ENSG00000040731.
Subcellular location: Cell membrane
Subcellular location (Human Protein Atlas): Cell Junctions; Nucleoplasm
Pathways (Reactome):
Cell-Cell communication: Adherens junctions interactions
Gene Ontology:
Molecular function: beta-catenin binding; cadherin binding; calcium ion binding
Biological process: adherens junction organization; calcium-dependent cell-cell adhesion; cell migration; cell morphogenesis; cell-cell adhesion; cell-cell adhesion mediated by cadherin; cell-cell junction assembly; synaptic membrane adhesion; cell adhesion; homophilic cell-cell adhesion
Cellular component: adherens junction; catenin complex; plasma membrane; GABA-ergic synapse; glutamatergic synapse; membrane; postsynaptic specialization membrane; presynaptic active zone membrane; synapse
Genetic constraint (gnomAD): Loss-of-function variants: 15 observed, 35.28 expected, observed/expected ratio (o/e) 0.43, 90% interval 0.28 to 0.65. The upper end of that interval is the gene's LOEUF score, 0.65, which puts it in group 2 of 6, group 1 being the genes least tolerant of losing a copy. Missense variants: 475 observed, 584.44 expected, observed/expected ratio (o/e) 0.81, 90% interval 0.75 to 0.88. Synonymous variants: 199 observed, 217.96 expected, observed/expected ratio (o/e) 0.91, 90% interval 0.81 to 1.03.
Homologues: Orthologues: chimpanzee CDH10 (100% identical), macaque CDH10 (99% identical), pig CDH10 (98% identical), rabbit CDH10 (98% identical), mouse Cdh10 (97% identical), rat Cdh10 (96% identical), guinea pig CDH10 (85% identical), tropical clawed frog cdh10 (84% identical), zebrafish cdh10a (64% identical). Paralogues in human: CDH6 (73% identical), CDH9 (70% identical), CDH12 (61% identical), CDH7 (60% identical), CDH18 (59% identical), CDH20 (58% identical), CDH11 (57% identical), CDH8 (57% identical), CDH22 (50% identical), CDH24 (47% identical), CDH19 (47% identical), CDH5 (39% identical), and 21 more.